C11orf98 (chromosome 11 open reading frame 98)
Description:
Promotes sister chromatid cohesion by enhancing recruitment of CDCA5/sororin to chromatin during S phase and stimulating the anti-WAPL activity of CDCA5. Associates with the pre-60S ribosome and may be involved in pre-60S ribosome assembly.
Synonyms: C11orf48
Tractability: Small molecule: a structure with a bound ligand is known. PROTAC: ubiquitination databases record sites on it.
Gene: Protein-coding gene on chromosome 11 (62,662,817 to 62,665,210, reverse strand). Ensembl gene ENSG00000278615.
Subcellular location: Nucleus; Nucleus, nucleolus
Gene Ontology:
Molecular function: protein binding
Biological process: positive regulation of sister chromatid cohesion
Cellular component: nucleolus; nucleus
Genetic constraint (gnomAD): Loss-of-function variants: 6 observed, 8.34 expected, observed/expected ratio (o/e) 0.72, 90% interval 0.39 to 1.41. That is too few expected variants to judge how well the gene tolerates losing a copy. Missense variants: 107 observed, 105.7 expected, observed/expected ratio (o/e) 1.01, 90% interval 0.87 to 1.19. Synonymous variants: 49 observed, 41.38 expected, observed/expected ratio (o/e) 1.18, 90% interval 0.94 to 1.5.
Homologues: Orthologues: guinea pig C11orf98 (85% identical), mouse 1810009A15Rik (83% identical), pig C11orf98 (81% identical), rat C1h11orf98 (79% identical), tropical clawed frog lbhd1 (59% identical).
Diseases named in the same sentence as C11orf98 in open-access papers:
C11orf98 is named in the same sentence as 1 disease in open-access papers, as found by Europe PMC text mining. Sharing a sentence is not in itself a finding about the gene and the disease.
C11orf98 shares sentences with these, for which no sentence is quoted: infection (2 papers).